SPOCD1 (SPOC domain containing 1)
Description:
Protein adapter that acts as an essential executor of PIWIL4-piRNA pathway directed transposon DNA methylation and silencing in the male embryonic germ cells. Recruited to young transposons, which are specifically marked with histone H3 trimethylated at both 'Lys-4' and 'Lys-9' (H3K4me3K9me3), via its association with SPIN1 chromatin reader, and associates with the de novo DNA methylation machinery and repressive chromatin remodeling complexes (By similarity). Following this, PIWIL4 engages with nascent transposable element transcript to direct piRNA-directed DNA methylation. Not required for piRNA biosynthesis (By similarity).
Synonyms: FLJ25348; PPP1R146
Tractability: No criterion of Open Targets' tractability assessment is met for any kind of drug.
Gene: Protein-coding gene on chromosome 1 (31,790,422 to 31,816,022, reverse strand). Ensembl gene ENSG00000134668.
Subcellular location: Nucleus; Chromosome
Subcellular location (Human Protein Atlas): Cytosol; Nucleoli; Nucleoplasm
Pathways (Reactome):
Gene expression (Transcription): Regulation of endogenous retroelements by Piwi-interacting RNAs (piRNAs)
Gene Ontology:
Molecular function: protein binding; protein-macromolecule adaptor activity
Biological process: spermatogenesis; transposable element silencing by piRNA-mediated DNA methylation; transposable element silencing by piRNA-mediated heterochromatin formation; DNA-templated transcription
Cellular component: chromosome; nucleus
Genetic constraint (gnomAD): Loss-of-function variants: 63 observed, 88.51 expected, observed/expected ratio (o/e) 0.71, 90% interval 0.58 to 0.88. The upper end of that interval is the gene's LOEUF score, 0.88, which puts it in group 3 of 6, group 1 being the genes least tolerant of losing a copy. Missense variants: 1,331 observed, 1,454.8 expected, observed/expected ratio (o/e) 0.91, 90% interval 0.87 to 0.96. Synonymous variants: 569 observed, 579.47 expected, observed/expected ratio (o/e) 0.98, 90% interval 0.92 to 1.05.
Homologues: Orthologues: chimpanzee SPOCD1 (98% identical), macaque SPOCD1 (90% identical), pig SPOCD1 (55% identical), rabbit SPOCD1 (54% identical), dog SPOCD1 (45% identical), mouse Spocd1 (42% identical), Drosophila melanogaster pps (16% identical). Paralogues in human: PHF3 (20% identical), DIDO1 (17% identical).
Diseases named in the same sentence as SPOCD1 in open-access papers:
SPOCD1 is named in the same sentence as 22 diseases in open-access papers, as found by Europe PMC text mining. Sharing a sentence is not in itself a finding about the gene and the disease. The quoted sentences say what the papers report.
bladder cancer (7 papers, 2018 to 2025). "Many studies demonstrated the upregulation of SPOCD1 in bladder cancer, gastric cancer, glioma, and osteosarcoma." (PMID 36830578, 2023). "Some other studies also demonstrated that SPOCD1 was highly expressed bladder cancer and gastric cancer, stimulating cell proliferation, migration, and invasiveness." (PMID 35092558, 2022). "Curiously, SPOCD1 was downregulated in progressive bladder cancer patients, which is particularly interesting as it further supports the emerging molecular distinction between bladder cancer and UTUC." (PMID 40867248, 2025). "On the contrary, the expression of SPOCD1 was downregulated in bladder cancer." (PMID 35646092, 2022). "Five genes in our prognostic model, ANXA1, MAP1B and SPOCD1 have been reported in bladder cancer, however DOK7 and FKBP10 has not been studied in bladder cancer." (PMID 36709279, 2023). "It has been revealed that SPOCD1 can be used to distinguish patients with progressive and non-progressive bladder cancer." (PMID 35646092, 2022).
glioma (6 papers, 2020 to 2024). A benign or malignant brain and spinal cord tumor that arises from glial cells (astrocytes, oligodendrocytes, ependymal cells). "Most notably, some studies have explored the biological function of SPOCD1 in human cancer, such as gastric cancer, clear cell renal cell carcinoma, ovarian cancer, osteosarcoma, and glioma." (PMID 35646092, 2022). "Emerging evidence has indicated that the expression of SPOCD1 is a prognostic factor in several tumors, including gastric cancer, clear cell renal cell carcinoma, ovarian cancer, osteosarcoma, and glioma." (PMID 35646092, 2022). "SPOCD1 encodes a protein that pertains to the transcription factor S-II (TFIIS) family of transcription factors and accelerates the proliferation and metastasis of glioma cells by up-regulating PTX3." (PMID 35941292, 2022). "Several studies revealed that SPOCD1 was highly expressed in glioma and gastric cancer." (PMID 35646092, 2022). "Besides, SPOCD1 promotes the metastasis and proliferation of glioma cells via PTX3." (PMID 35646092, 2022). "In glioma cells, PTX3 is suggested to be regulated by spen paralogue and orthologue C-terminal domain containing 1 (SPOCD1), further highlighting its involvement in metastatic processes." (PMID 39594709, 2024). "SPOCD1 was also shown to upregulate PTX3, thus enhancing glioma cells’ ability to proliferate and metastasize." (PMID 36830578, 2023). "Furthermore, the expression levels of several genes (PLOD3, SLC20A1, ADAM9, FBLIM1, SPOCD1, P4HB, PROS1 and SELENON) were positively correlated with glioma grades." (PMID 32091665, 2020).
ovarian carcinoma (6 papers, 2022 to 2023). A malignant neoplasm originating from the surface ovarian epithelium. "Our published papers have shown that SPOC Domain Containing 1 (SPOCD1) accelerated ovarian cancer progression and inhibited apoptosis through PI3K/AKT pathway." (PMID 35259044, 2022). "It has also been reported that the significantly expressed SPOCD1 accelerated the progression of ovarian carcinoma and inhibited cell death (apoptosis) via the PI3K/AKT pathway." (PMID 35267472, 2022). "Our published papers have shown that SPOCD1 accelerated ovarian cancer progression." (PMID 35259044, 2022). "SPOCD1 encodes a TFIIS-family transcription factor and has been reported to promote the progression and metastasis of several types of cancer, including bladder and ovarian cancers, and osteosarcoma and glioblastoma, by activating signaling pathways such as the EGFR and VEGFR pathways." (PMID 35976950, 2022). "SPOCD1 could inhibits cell apoptosis through PI3K/AKT pathway and accelerates ovarian cancer progression." (PMID 36709279, 2023).
gastric cancer (5 papers, 2018 to 2024). A primary or metastatic malignant neoplasm involving the stomach. "For example, eIF3a mutation was found to be related to acquired chemotherapy resistance in lung cancer, and a low-frequency missense variant in SPOCD1 was associated with reduced risk of gastric cancer." (PMID 38589831, 2024). "They found that SPOCD1 was subjected to expression in gastric cancer and that silencing this gene severely hampered the formation of xenograft tumors in nude mice and the ability of gastric cancer cells to proliferate and invade." (PMID 36830578, 2023).
osteosarcoma (4 papers, 2022 to 2023). A usually aggressive malignant bone-forming mesenchymal neoplasm, predominantly affecting adolescents and young adults. "Moreover, SPOCD1 serves as a pro-oncogenic factor in osteosarcoma by enhancing cell proliferation and suppressing cell apoptosis." (PMID 36830578, 2023). "SPOCD1 was up-regulated and promoted cell proliferation in osteosarcoma cell lines." (PMID 35267472, 2022).
colorectal cancer (1 paper, 2023). A primary or metastatic malignant neoplasm that affects the colon or rectum. "The biological role of the spen paralogue and orthologue C-terminal domain containing 1 (SPOCD1) has been investigated in human malignancies, but its function in colorectal cancer (CRC) is unclear." (PMID 36830578, 2023). "Moreover, SPOCD1 expression was shown to correlate with macrophages and other immune cells (dendritic cells, CD8+ T cells, neutrophils, and CD4+ T cells) by searching the TIMER database, suggesting that these cell types may participate in the immunological immersion process of colorectal cancer." (PMID 36830578, 2023).
esophageal squamous cell carcinoma (1 paper, 2022). Esophageal squamous cell carcinoma (ESCC) is a type of esophageal carcinoma (EC) that can affect any part of the esophagus, but is usually located in the upper or middle third. "In the study, we aimed to explore and analyze the potential function of SPOC Domain Containing 1 (SPOCD1) in esophageal squamous cell carcinoma (ESCC)." (PMID 35646092, 2022).
Infertility (1 paper, 2025). "SPOCD1 is involved in piRNA-mediated DNA methylation targeting TE and its deficiency leads to male-specific infertility." (PMID 40847283, 2025).
keloid (1 paper, 2025). An irregularly shaped, elevated mark on the skin caused by deposits of excessive amounts of collagen during wound healing. "The heatmap and Volcano Plot analysis identified 2510 differentially expressed genes (DEGs) including SPOCD1 between keloid and normal skin tissue." (PMID 39820341, 2025). "Conversely, the decrease of SPOCD1 has significant inhibition on the expression of col1 and col3 which are the main extracellular matrix component of keloid." (PMID 39820341, 2025). "In these simulations, we have also confirmed the inhibitory impact of si-SPOCD1 on keloid growth, diminishing the propensity for KD to form new blood vessels, and the modulation of IFNγ on SPOCD1." (PMID 39820341, 2025). "Through RNA sequencing (RNA-seq), we discovered that SPOCD1, which plays a regulatory role in some kinds of cells’ death, is overexpressed in keloid." (PMID 39820341, 2025). "This suggests that SPOCD1 is likely involved in cell ferroptosis, which is precisely the focus of our ongoing research about keloid." (PMID 39820341, 2025). "The intensity of fluorescence staining also show that SPOCD1 is highly expressed in keloid as fluorescence intensity of keloid is 2.3 times higher than that of normal skin and so as the western blotting results." (PMID 39820341, 2025). "Meanwhile, Si-IFNγ combined with si-SPOCD1 can further reduce the impact of si-IFNγ on keloid tissue, thereby reducing the cell migration rate." (PMID 39820341, 2025). "Followed by SPOCD1 was discovered significantly expressed in keloid, cellular distribution and quantitative analysis of SPOCD1was detected with either immunofluorescence and western blotting." (PMID 39820341, 2025). "Ex-vivo explant keloid culture has also confirmed that the reduction of SPOCD1 helps to reduce the proliferation rate of KFs, inhibit the angiogenesis of keloid scars, and thus inhibit keloid formation." (PMID 39820341, 2025). "Hence, the increase rate of CD31+/ CD34+ implies that si-SPOCD1 and si- IFNγ + SPOCD1 can diminish the stemness of vascular endothelial cells, curtail the neovascularization within the vascular endothelium of keloid, thereby inhibiting the growth of keloid." (PMID 39820341, 2025). "Thus, IFNγ signaling paired with SPOCD1 is a natural keloid ferroptosis promoting mechanism and a mode of action of CTLs." (PMID 39820341, 2025). "Targeting SPOCD1 pathway is a potential anti-keloid approach." (PMID 39820341, 2025). "The regulatory relationship between IFNγ and SPOCD1 may emerge as a novel target for treating keloid and preventing their recurrence." (PMID 39820341, 2025). "Therefore, we speculate that the regulatory activity of SPOCD1 in keloid is also related to DNA methylation." (PMID 39820341, 2025). "Here, we discover interferon (IFN)γ could induce KFs ferroptosis through inhibiting SPOC domain-containing protein 1 (SPOCD1), serving as a mode of action for CD8+T cell (CTL)-mediated keloid killing." (PMID 39820341, 2025).
migraine (1 paper, 2025). "Our analyses revealed 283 genes, including some newly associated with migraine: MAML3, CELF4, IRX1, ASXL1, SPOCD1, CXCL, and TLR4." (PMID 41420111, 2025).
thyroid cancer (1 paper, 2022). "Several hypermethylated genes (GALNTL6, HTR7, SPOCD1, CDH16 and GRM5) related to thyroid cancer have been discovered to be up-regulated in our study, as were investigated in other reports to mentioned in the following text." (PMID 35267472, 2022).
tumor (6 papers, 2022 to 2025). "The AUC of the ROC curve for SPOCD1 expression was 0.906 (95% CI = 0.874–0.938), indicating the excellent predictive potential for distinguishing tumor tissues from normal tissues." (PMID 36830578, 2023). "Based on the expression value of SPOCD1, we divided the tumor samples from our center data and TCGA data set into high SPOCD1 expression group and low SPOCD1 expression group according to the median value." (PMID 35646092, 2022). "As for ECSS, the tumor patients in TCGA-ESCC were divided into two groups: high expression of SPOCD1 group and low expression of SPOCD1 group." (PMID 35646092, 2022). "To analyze the relationship between the expression of SPOCD1 and immune cell infiltration, we calculated the proportion of immune cell infiltration in the tumor microenvironment by the CIBERSORT algorithm." (PMID 35646092, 2022). "It is known to all that SPOCD1 is an oncogene in several tumor types, and plays an essential role in the occurrence and development of tumors." (PMID 35646092, 2022). "We also evaluated how SPOCD1 mRNA levels correlate with the tumor immune microenvironment (TIME)." (PMID 36830578, 2023). "Tumor cells were more sensitive to these medicines when the SPOCD1 level was upregulated." (PMID 36830578, 2023). "In recent years, many studies have revealed that the expression of SPOCD1 was significantly related to the development and occurrence of the tumor, and they may be used as ideal biomarkers of the tumor." (PMID 35646092, 2022). "Consequently, we compared the difference of SPOCD1 between tumor samples and normal samples in the two data sets after selecting SPOCD1 as the target gene." (PMID 35646092, 2022). "HEYL, SLC2A3, and FBN1 were found to mediate tumor progression and chemoresistance mainly by facilitating angiogenesis and EMT, while CERCAM, ANXA1, and SPOCD1 promoted tumor progression through the PI3K/AKT and EGFR signaling pathways." (PMID 39033778, 2024).
cancer (5 papers, 2018 to 2023). A tumor composed of atypical neoplastic, often pleomorphic cells that invade other tissues. "Suppression of SPOCD1 has shown promise as a potential cancer therapy method, and it is widely regarded as a promising treatment and prognostic target for cancer." (PMID 36830578, 2023). "Using information from the TCGA database, we examined the SPOCD1 gene expression profiles between various human malignant cancers and normal samples." (PMID 36830578, 2023). "Together, the study provides evidence for the clinical and functional significance of SPOCD1, as well as its potential as a novel strategy for cancer treatment, providing momentous evidence for exploring the role of SPOCD1 in ESCC." (PMID 35646092, 2022). "We began our investigation by assessing SPOCD1 mRNA expression in a TCGA pan-cancer sample." (PMID 36830578, 2023). "In the study, multicancer invasiveness signature and adaptive immune response was correlated with the expression of SPOCD1, which revealed that SPOCD1 may play a crucial role in immune response and modulating cancer invasion in ESCC." (PMID 35646092, 2022). "In addition, SPOCD1 is considered to be an attractive therapeutic and prognostic target for cancer, and inhibition of SPOCD1 may be a feasible cancer treatment strategy." (PMID 35646092, 2022). "Notably, macrophages, which are key players in regulating angiogenesis, cancer cell proliferation, metastasis, immunosuppression, extracellular matrix remodeling, checkpoint blockade immunotherapy as well as chemoresistance, were found to have the strongest link to SPOCD1 expression." (PMID 36830578, 2023). "Taken together, these results strongly supported the excellent anti-cancer effects of BRD4 inhibition by JQ1 in sunitinib-resistant ccRCC and suggested that SCG5, SPOCD1, RGS19, and ARHGAP22 may be novel direct targets of the epigenetic reader BRD4 in sunitinib-resistant ccRCC." (PMID 29796168, 2018).
SPOCD1 also shares sentences with these, for which no sentence is quoted: glioblastoma (2 papers); breast carcinoma (1); clear cell renal cell carcinoma (1); colon adenocarcinoma (1); head and neck squamous cell carcinoma (1); lung carcinoma (1); pancreatic cancer (1); rectum adenocarcinoma (1); Stroke (1).